BRCA2 (BRCA2 DNA repair associated)
Diseases named in the same sentence as BRCA2 in open-access papers (continued):
Sharing a sentence is not in itself a finding about the gene and the disease.
breast cancer (continued). "The prevalence of pathogenic BRCA2 mutations in breast cancer cases is, however, less than for BRCA1 in most of Western Europe and North America, which may be why reports on the outcome of early diagnosis with MRI in carriers of pathogenic BRCA2 mutations are even sparser." (PMID 27087880, 2016). "However, prevalence of BRCA1 and BRCA2 mutations is low in sporadic breast cancer patients." (PMID 27283966, 2016). "Women at high risk for breast cancer and OVCA, having a mutation in either BRCA1 or BRCA2 genes, may prophylactically take selective estrogen receptor modulators (SERMs), such as 4-hydroxytamoxifen (4OHT), to decrease their risk of developing breast cancer." (PMID 26879975, 2016). "Indeed, at least 60–70 % of all breast cancers caused by an inherited BRCA1 germline mutation are diagnosed as TNBC, while inactivation of the second major breast cancer susceptibility gene BRCA2 is more frequently observed in hormone receptor-positive breast cancers." (PMID 27756336, 2016). "Additionally, we provide evidence that ATM, ATR and BRCA2 may be associated with CRC in addition to the known association with breast cancer." (PMID 27294413, 2016). "Women who have inherited mutations in BRCA1 or BRCA2 are at greatly increased risk of developing breast cancer (BC) and ovarian cancer (OC)." (PMID 27836010, 2016). "Previous studies have provided some evidence, in known breast cancer susceptibility genes BRCA1 and BRCA2, of genetic variants associated with allelic expression differences which could affect the risk of breast cancer in mutation carriers through altering expression levels of the wild-type allele." (PMID 27792995, 2016). "The vast majority of cancers arise spontaneously hence their prediction is impossible although certain populations may benefit such as those predisposed to certain cancers e.g. women who carry the defective BRCA1 or BRCA2 genes which predispose to breast cancer." (PMID 27412241, 2016). "Similarly, females with BRCA2 mutations have an 85% chance of developing breast cancer." (PMID 25624909, 2015). "However, the apparent enrichment of BRCA1/BRCA2 mutation carriers among ovarian cancer cases with a prior or coincident invasive breast cancer would advocate genetic testing of ovarian cancer cases with breast cancer in the French Canadian population." (PMID 25884701, 2015). "Here we have shown that BRCA2 mutation carriers with the subclade T1a1 have between 30% and 50% less risk of breast cancer than those with other clades, which, if validated, is a clinically meaningful risk reduction and may influence the choice of risk management strategies." (PMID 25925750, 2015). "Given that both FANCD2 and BRCA2 mutations (in homozygous state) cause the same chromosomal instability syndrome called Fanconi anemia, it is likely that breast cancers that arise in carriers of a mutation in these genes may have similar clinical characteristics." (PMID 25093046, 2014). "In addition, since mutations in BRCA1 and BRCA2 were investigated within the locations reported in human breast cancer, cats may carry BRCA1 and BRCA2 mutations in different gene locations." (PMID 24004841, 2013). "Although two major breast cancer susceptibility genes, BRCA1 and BRCA2, have been identified accounting for 20% of breast cancer genetic risk, identification of other susceptibility genes accounting for 80% risk remains a challenge due to the complex, multi-factorial nature of breast cancer." (PMID 23967281, 2013). "Until recently, the process of SV discovery in disease genes like BRCA1 and BRCA2 required gene-specific probes to amplify and quantify the genomic DNA structure and amount, which made it difficult to identify new genes contributing to breast cancer risk though mechanisms such as SV." (PMID 24358278, 2013).
breast cancer (continued). "Combining this BRCA2-specific SNP with 13 other breast cancer risk SNPs also known to modify risk in BRCA2 mutation carriers, we were able to derive a risk prediction model that could be useful in helping women with BRCA2 mutations weigh their risk-reduction strategy options." (PMID 23544012, 2013). "However, as the PALB2 c.1592delT founder mutation, with a frequency of roughly 1% also in Finnish breast cancer cases unselected for their family history of disease, increases the risk of breast cancer in a way comparable to that of BRCA2, targeted clinical testing for c.1592delT seems appropriate." (PMID 23941127, 2013). "Consequently, germ-line mutations in BRCA2 predispose women to a high risk of breast cancer." (PMID 23071527, 2012). "Similarly, the canine BRCA2 gene locus has been associated with mammary tumors in female dogs." (PMID 23071527, 2012). "Therefore, canine BRCA2 may be a good model for studying human breast cancer caused by BRCA2 mutations." (PMID 23071527, 2012). "Furthermore, there was suggestive evidence that the minor allele of SNP rs4942440, which is associated with higher BRCA2 expression, is also associated with a reduced risk of breast cancer (per-allele hazard ratio (HR) = 0.85, 95% confidence interval (CI) = 0.72 to 1.00, P-trend = 0.048)." (PMID 22513257, 2012). "Interestingly, all nine breast cancers with BRCA1 or BRCA2 mutations clustered together." (PMID 22608084, 2012). "Therefore, we conclude that canine BRCA2 may be a good model for studying human breast cancer caused by human BRCA2 mutations." (PMID 23071527, 2012). "The association patterns between these common variants and breast cancer risk for BRCA1 and BRCA2 mutation carriers are in general different, and mostly reflect differences in the associations of these single-nucleotide polymorphism (SNPs) with estrogen receptor (ER) status of breast cancer." (PMID 22348646, 2012). "Therefore, one of the parents of a FA-D1 patient will be a heterozygous carrier of a “severe” inactivating BRCA2 mutation and may thus have an increased risk for breast cancer and other BRCA2-associated cancers." (PMID 22778927, 2012). "Although further confirmation is required to show the similarity between canine and human BRCA2 functions, cBRCA2 is speculated to have a function similar to that of hBRCA2 in mammary tumors and may be a useful model of human breast cancer resulting from BRCA2 mutations." (PMID 23071527, 2012). "This is the case for the c.68_69del and c.5266dup mutations in BRCA1 and c.5946del mutation in BRCA2 (until recently referred in the literature as 185delAG, 5382insC and 6174delT, respectively) which are found in 10-12% of Ashkenazi Jewish women diagnosed with breast cancer." (PMID 22185575, 2011). "Although two of the studies reported no significant breast cancer risk reduction associated with prophylactic oophorectomy in BRCA2 carriers, the meta-analysis suggested that prophylactic oophorectomy offered a 53% reduction in risk of first primary breast cancer (95% CI 0.26–0.84)." (PMID 21487411, 2011). "Moreover, ongoing GWAS in BRCA1 and BRCA2 mutation carriers may also identify further modifiers of breast cancer risk for mutation carriers." (PMID 22053997, 2011). "We used genotype data on up to 11,421 BRCA1 and 7,080 BRCA2 carriers, of whom 4,310 had been affected with breast cancer and had information on either ER or PR status of the tumour, to assess the associations of 12 loci with breast cancer tumour characteristics." (PMID 22053997, 2011). "Similar work involving large genomic alterations in BRCA2 could also be beneficial, but it is likely to have less impact given current data which suggests there is a broader morphological phenotype of breast cancers carrying these mutations and the extreme rarity of these mutations in BRCA2." (PMID 21281505, 2011).
breast cancer (continued). "In a segregation analysis of families identified through breast cancer cases diagnosed before age 55, the residual familial clustering after accounting for BRCA1 and BRCA2 mutations could be explained by a large number of low penetrance genes with multiplicative effects on breast cancer risk." (PMID 21060860, 2010). "However, it remains possible that unique variants with smaller effects, or rarer variants (not evaluated in this experiment), may be specific modifiers of breast cancer risk in BRCA2 carriers." (PMID 21060860, 2010). "This study provides evidence that the SMAD3 gene, which encodes a key regulatory protein in the transforming growth factor beta signalling pathway and is known to interact directly with BRCA2, may contribute to increased risk of breast cancer in BRCA2 mutation carriers." (PMID 21114847, 2010). "Furthermore, in a prospective study of 139 women with BRCA1 or BRCA2 mutations, after a mean follow-up of 3 years, breast cancer developed in 8 of 63 women who had elected surveillance, but in none of the 76 BRCA mutations carriers who had undergone prophylactic surgery." (PMID 20961453, 2010). "Further analysis has shown that allelic variation at FGFR2, TNRC9, 8q24, 2q35, and 5p12 is associated with physiological characteristics of breast tumors, such as ER status, and specific FGFR2, MAP3K1, and TNRC9 variants may interact with BRCA1 and BRCA2 mutations to increase breast cancer risk." (PMID 21037853, 2010). "About one-third of the genetic variants in BRCA1 and 50% of those found in BRCA2 reported by the Breast Cancer Information Core are considered genetic variants of unknown clinical significance, also known as unclassified variants (UVs), because of the uncertainty about their cancer risks." (PMID 19200354, 2009). "The use of family cancer burden in adjusting risks to carriers is already used in the BOADICEA programme and the Manchester score could also be used as a bench mark of where in the range of 40–90% breast cancer risk a women should be steered, especially for BRCA2." (PMID 18513387, 2008). "However BRCA1 and BRCA2 may account for less than 40% of all familial breast cancer; multiple low penetrance breast cancer predisposition genes are likely to account for the rest." (PMID 17697367, 2007). "In conclusion, our study allowed to assess that BRCA2-8765delAG, arising in conjunction with several and clearly distinct genetic haplotypes, may be generated in an independent manner and at a frequency higher than other BRCA2 mutations among breast cancer families world-wide." (PMID 17640379, 2007). "Hence there is a need for screening a larger number of samples to investigate the role of BRCA1/BRCA2 gene mutations in the high-risk group of familial as well as early onset cases, which forms the largest group of breast cancer patients in the Indian population." (PMID 17018160, 2006). "However, having two or more therapeutic abortions may be associated with a lowered risk of breast cancer among BRCA2 carriers." (PMID 16563180, 2006). "Finally, in the context of genetic counselling, specific tumour characteristics may help evaluate the possibility of a BRCA1 or BRCA2 mutation and the need for mutation testing in a family with a history of breast cancer." (PMID 15987451, 2005). "Some of this excess risk of prostate cancer may be due to mutations in BRCA1 and BRCA2." (PMID 11875732, 2002). "These drugs are used to treat many breast cancer subtypes, including HER2-positive, triple negative, hormone receptor-positive, and hereditary breast cancers driven by germline mutations in Breast Cancer genes 1 and 2 (BRCA1 and BRCA2)." (PMID 41536815, 2026).
breast cancer (continued). "Reported lifetime breast cancer risks for women with LFS range up to 80–90%, surpassing the risk linked to BRCA1- and BRCA2-related hereditary breast cancer, whereas ESMO guidelines indicate a substantially lower lifetime risk of around 40%." (PMID 41528496, 2026). "BRCA2 PVs predominantly lead to estrogen receptor (ER)-positive/HER2-negative breast cancers, which exhibit more aggressive phenotypes compared to sporadic cases." (PMID 42032759, 2026). "Background/Objectives: Prophylactic mastectomy can significantly reduce the risk of breast cancer in patients carrying gene mutations such as BRCA1 and BRCA2." (PMID 41827488, 2026). "Background/Objectives: Contralateral breast cancer (CBC) is a significant concern among breast cancer survivors, particularly in those with moderator-high penetrance germline mutations such as BRCA1, BRCA2, CHEK2, and ATM." (PMID 41976331, 2026). "In one patient (Patient 4) with a BRCA2 GPV, a family history of breast cancer facilitated discussions regarding diagnostic evaluation for the patient’s relatives." (PMID 40926019, 2026). "Among the group who entered the MRI-screening program, the age-adjusted HR for breast cancer mortality was 0.20 (95% CI: 0.10 - 0.43; P < 0.001) for women with BRCA1 and 0.87 (95% CI: 0.10 - 17.25; P = 0.93) for women with BRCA2 variants." (PMID 41488281, 2026). "We investigated the contribution of non-coding variation to hereditary breast cancer by analyzing intronic variants and 5' upstream regions of BRCA1, BRCA2 and PALB2 in the BEACCON case-control study of over 11,000 participants." (PMID 41935071, 2026). "Compared to female breast cancer (FBC), MBC shows a higher prevalence of hormone receptor positivity and distinct germline predispositions, most frequently pathogenic variants in BRCA2 and CHEK2." (PMID 41919251, 2026). "Approximately 10% of breast cancer is inherited; women with deleterious germline BRCA1 or BRCA2 mutations have a lifetime 60–70% risk of breast cancer." (PMID 41350536, 2025). "Among 288 women who developed breast cancer during the trial, 19 (6.6%) carried BRCA1 (n = 8) or BRCA2 P/LP variants (n = 11)." (PMID 39858629, 2025). "This study demonstrated similar results, but this is the first report of ILC, BRCA2, and bone metastasis associated with AKT pathway alterations in luminal recurrent breast cancer." (PMID 39466567, 2025). "This is compared with the guidance in place at the time of the meeting, which stipulated that individuals with a GPV in BRCA1/BRCA2/PALB2 were only eligible for breast cancer surveillance at age 25–30 years if they reached a 10-year risk of 8% or greater." (PMID 41159931, 2025). "Women with breast cancer, including underrepresented populations, received germline testing to determine P/LP variants in BRCA1 and BRCA2 genes." (PMID 40952741, 2025). "The breast cancers are associated with three types of mutations: BRCA1, BRCA2, and Sporadic mutations." (PMID 41542084, 2025). "The few studies investigating the difference in magnitude of the association between OC use and breast cancer risk depending on genetic predisposition have primarily focused on carriers of the BRCA1 and BRCA2 mutations." (PMID 41327462, 2025). "Brunei BRCA2 carriers were found to be more likely to have family history of breast and/or ovarian cancers, and having more first-degree relatives affected with breast cancer." (PMID 40531958, 2025).
breast cancer (continued). "The correlation analysis of HA, CD44, BRCA1, and BRCA2 showed only one strong correlation, BRCA1 and BRCA2 in breast cancer (r = 0.7; p < 0.0001), while in the case of colorectal cancer this correlation was much weaker (r = 0.5; p = 0.02)." (PMID 41373491, 2025). "Inherited gene mutations are found in less than 25% of breast cancer cases, and of these genes, BRCA1 and BRCA2 are the most common cause of hereditary breast cancer." (PMID 40806826, 2025). "Oncogenic dominant variants were observed in 4.2% of our cohort, of whom 2 individuals presented with P variants in BRCA2 and PALB2, both being linked to breast cancer and accounting together for 0.4% of our cohort." (PMID 40679974, 2025). "Key consensus points established specific age-based recontact practices for high penetrance CSGs, BRCA1, BRCA2 and PALB2, including recontact at 25 years to review breast cancer risk management and ovarian cancer risk management at gene-specific ages." (PMID 41159931, 2025). "Conversely, BRCA2, ATM, PALB2, and CHEK2 were more commonly associated with later-onset breast cancer, for which the penetrance estimates ranged from 19% to 31% by age 60 years." (PMID 39858629, 2025). "Mutations in either BRCA2 or PALB2 reduce the HR repair capacity, thereby increasing the risk of breast cancer and potentially prime for cardiotoxic events." (PMID 39621070, 2025). "The average cumulative risk of developing breast cancer by the age of 80 years is 72% [95%CI = 65–79] for BRCA1 carriers and 69% [95%CI = 61–77%] for BRCA2 GPV carriers, compared to a lifetime risk of 12.9% in the general population." (PMID 40427184, 2025). "In our study of 309 affected BRCA1/2 and PALB2 carriers with operable breast cancer, the receipt of chemotherapy following an index breast cancer diagnosis was 70% overall but varied from 57% in BRCA2 carriers to upwards of 80% in BRCA1 and PALB2 carriers." (PMID 40275390, 2025). "The aim of this study is to review and summarize the existing data on genetic modifiers of breast cancer risk in female BRCA1 and BRCA2 pathogenic variants carriers." (PMID 40296163, 2025). "Triple-negative breast cancers are likely to be BRCA1 mutation positive, while HER2 amplification is uncommon in BRCA1 and BRCA2 mutation carriers." (PMID 39885374, 2025). "It is established that mutations in the BRCA1 or BRCA2 gene underlie sensitivity to PARP inhibitors in cancer cells, most notably in breast cancer." (PMID 40025053, 2025). "The most interesting finding of the MetaCore analysis was the significant correlation between GNPDA1 and BRCA1 and BRCA2 in breast cancer cells." (PMID 40278313, 2025). "From our analysis, only a minority of genes complied with the criteria: 69 and 10 genes in BRCA1 and BRCA2 mutated breast cancers, respectively, and 10 and 9 genes in BRCA1 and BRCA2 mutated ovarian cancers, respectively." (PMID 40647506, 2025).